LDHA (lactate dehydrogenase A)
Diseases named in the same sentence as LDHA in open-access papers (continued):
Sharing a sentence is not in itself a finding about the gene and the disease.
tumor (continued). "Lactate dehydrogenase A (LDHA) is a tumor-promoting enzyme that preferentially catalyzes the conversion of pyruvate to lactate." (PMID 40563460, 2025). "Among the 7 HRGs included in the hypoxia risk score model constructed in this study, these 6 genes (LDHA, PGK1, PFKP, DCN, LOX, FBP1) have been extensively reported in previous studies for their roles in tumor hypoxia response and progression." (PMID 40464853, 2025). "α-Enolase increases glycolysis and tumor cell proliferation, while LDHA is required to produce NAD+, a cofactor required for glycolysis to provide sufficient energy and material basis for tumor cell proliferation." (PMID 40718778, 2025). "Galloflavin directly binds and inhibits LDHA activity, reducing lactate production and inducing apoptosis in tumor cells." (PMID 40443721, 2025). "PSTMB effectively inhibits LDHA activity, targets glucose metabolism, reduces lactate production, and increases induction of apoptotic cell death to reduce tumor cell proliferation." (PMID 41041328, 2025). "Studies have shown that LDHA inhibitors can effectively reduce lactate levels by blocking the final step of glycolysis, thereby inhibiting tumor progression." (PMID 41473784, 2025). "Enhanced lactate production driven by tumor-intrinsic LDHA not only fuels tumor growth but also imposes a profound suppressive effect on antitumor immunity." (PMID 41152975, 2025). "The deacetylation of BMAL1 by lactate/interleukin-1 beta (IL-1β) amplifies LDHA expression and tumor growth." (PMID 40725147, 2025). "The overexpression of LDHA in non-small cell lung cancer (NSCLC) is primarily regulated by hypoxia-inducible factors (HIFs), which activate LDHA transcription under hypoxic conditions prevalent in tumours." (PMID 41154605, 2025). "Lactate dehydrogenase A (LDHA) plays a crucial role in converting pyruvate to lactate in tumor lactate metabolism." (PMID 39870616, 2025). "Given the upregulation of LDHA mRNA expression in the datasets, coupled with documented increase of LDHA protein expression in tumour cells under hypoxic conditions, we sought to detect LDHA protein expression in hypoxic pulmonary arteries and PAECs." (PMID 40629253, 2025). "Histone lactylation not only meets the energy and biosynthetic needs of tumor cells by modifying important metabolic enzymes, such as LDHA, but also offers a means for the survival of oncogenic signaling pathways." (PMID 39968078, 2025). "Silencing LDHA or treatment with the LDHA inhibitor FX11 suppresses tumor growth in CAFs-rich PDAC models." (PMID 41152975, 2025). "Mechanistically, PSMD14 stabilizes lactate dehydrogenase (LDHA) through deubiquitination, leading to abnormally elevated lactate levels in tumor cells, which in turn drives increased lactylation at the H3K18 site (H3K18la)." (PMID 41051446, 2025). "The LDHA clinical trial has depicted that inhibiting LDHA expression leads to the reduction of cell proliferation, a marked delay in tumor migration, and in vivo tumorigenesis." (PMID 39997327, 2025). "These developments highlight a key clinical imperative: the design of LDHA inhibitors with optimized selectivity, pharmacokinetic properties, and tumor-penetrating capabilities." (PMID 40948941, 2025). "Targeting tumor acidosis via LDHA inhibition and MCT blockade represents a promising strategy to enhance NK cell‐based immunotherapy." (PMID 40959206, 2025). "have delineated that the upregulation of LDHA expression augments lactic acid production and histone lysine lactylation, diminishes tumor cell adhesion, and ultimately fuels the proliferation, invasion, and migration of breast cancer cells." (PMID 40165895, 2025). "In vivo, targeting 5'tRF-GlyGCC/LDHA signaling significantly suppresses tumor growth and enhances the efficacy of immunotherapy." (PMID 41309487, 2025). "Tumor acidity is influenced by the conversion of pyruvate to lactate, which is mostly carried out by lactate dehydrogenase A (LDHA)." (PMID 40230883, 2025).
tumor (continued). "In the same study, LDHA was identified as a direct target of miR-30d-5p, and loss of miR-30d-5p in GBC tissues was associated with worse prognosis, supporting a role of the miR-30d-5p/LDHA axis in driving aggressive tumor behavior." (PMID 41458606, 2025). "FX11, a small-molecule LDHA inhibitor, has shown promising anti-tumor efficacy in multiple preclinical models." (PMID 40593465, 2025). "Western blot showed that emodin downregulated the protein levels of HK2, PKM2 and LDHA in the nude mice, indicating that emodin inhibited glycolysis in the tumor of the nude mice." (PMID 41426311, 2025). "This dual metabolic-transcriptional reprogramming fosters an aggressive tumor phenotype, rendering it susceptible to combinatorial strategies involving BART6-5p antagomirs and LDHA inhibitors." (PMID 40977684, 2025). "Its mechanism primarily involves targeting lactate dehydrogenase A (LDHA), a key enzyme in tumor metabolism that catalyzes the conversion of pyruvate to lactate while regenerating NAD+." (PMID 40619414, 2025). "Clinically relevant glycolytic markers including HK2 and LDHA demonstrate strong correlations with advanced tumor stage, chemotherapy failure, and poor prognosis." (PMID 40977684, 2025). "Tumor cells exploit anaerobic glycolysis and lactate fermentation, catalyzed by LDHA and LDHB, to thrive in hypoxic conditions." (PMID 41029427, 2025). "To further identify the critical site through which circSMPD4 influences LDHA acetylation, we generated LDHA‐knockout tumor cell lines (HepG2‐R LDHA‐KO and Huh7‐R LDHA‐KO) and referenced the mass spectrometry results from an outstanding study." (PMID 40940312, 2025). "Inhibition of LDH, particularly the LDHA isoform, has been shown to reduce lactate production, thereby reprogramming tumour metabolism and inhibiting cancer cell proliferation." (PMID 41020792, 2025). "These infiltrating macrophages not only suppress anti-tumor immunity but also reinforce tumor growth by secreting LDHA-enriched extracellular vesicles that further promote glioma cell glycolysis and proliferation." (PMID 41450919, 2025). "Recent reviews highlight that inhibitors of LDHA or MCT1/MCT4 not only reduce tumour-cell growth but also “trap” the immunosuppressive tumour-microenvironment (TME) and enhance immunotherapy efficacy." (PMID 41394868, 2025). "Deletion of NAC1 in tumor cells leads to oxidative stress, reduced LDHA activity, and enhanced infiltration of CTLs within the tumor mass." (PMID 39773913, 2025). "The results showed that LDHA inhibition reduced the bioluminescence signals and the tumor sizes of the mice in the BCPAP-SOX12 group." (PMID 40593465, 2025). "Intriguingly, in U87MG group, LDHA knockdown led to decreased tumor growth, whereas LDHB knockdown exerted the opposite effect." (PMID 39895794, 2025). "Nanotechnology-based drug delivery platforms, such as LDHA-inhibitor-loaded nanoparticles, are under development to enhance tumor targeting and minimize systemic toxicity." (PMID 40843350, 2025). "Lactate dehydrogenase A (LDHA) is a subtype of the LDH enzyme that is highly expressed in many tumor cells." (PMID 40917751, 2025). "Conversely, in the U251MG group, LDHB knockdown significantly decreased the tumor size, volume, and weight, whereas LDHA knockdown exerted the opposite effect." (PMID 39895794, 2025). "LDHA initiates a positive feedback loop, reducing tumour cell stiffness and adhesion through H3K18 histone lactylation." (PMID 41190507, 2025). "S-palmitoylation is crucial in regulating tumor cell glycolysis and metabolic adaptation, particularly its impact on lactate dehydrogenase A (LDHA)." (PMID 40335986, 2025). "Cold atmospheric plasma (CAP) has been documented to suppress the activity of LDHA, emerging as a novel multi-modal approach in tumor treatment." (PMID 40057816, 2025). "Lactate dehydrogenase-A (LDH-A) converts pyruvate to lactate and is often upregulated in tumor cells, allowing for long-term energy generation under hypoxia." (PMID 40227635, 2025).
tumor (continued). "Collectively, these findings underscore the pivotal role of LDHA in cancer metabolism, tumor progression, and therapeutic resistance, with potential as a prognostic biomarker and therapeutic target." (PMID 41368023, 2025). "Dysregulation of key enzymes—including GAPDH, enolase 1 (ENO1), pyruvate kinase M2 (PKM2), and lactate dehydrogenase A (LDHA)—drives tumor growth and metastasis." (PMID 41204384, 2025). "LDHA is frequently overexpressed in various tumors and correlates with tumor size, clinical stage, and histological grade." (PMID 40565174, 2025). "This nanomaterial releases Dc during PDT for tumor treatment, inhibiting the activity and expression of LDHA, reducing lactate production, and further weakening tumor cell glycolysis and angiogenesis, thus enhancing the therapeutic effect of PDT." (PMID 40235732, 2025). "In hypoxic tumor cells, lactate production is driven by LDHA-mediated glycolysis, with subsequent MCT4-dependent lactate extrusion." (PMID 40565047, 2025). "In patients with HCC, the combination of anti-PD-1 therapy and LDHA inhibitors has demonstrated stronger anti-tumor effects than monotherapy with anti-PD-1 antibodies." (PMID 40584966, 2025). "Consistent with the in vitro results, in tumor tissues, the expression levels of LDHA and MCT4 in the CuB treatment group were decreased, the content of LA was reduced, and the content of PA was increased." (PMID 40944197, 2025). "Volcano plot analysis of differentially expressed genes showed that NDRG1 is markedly upregulated in tumor tissues, alongside several key metabolic genes, including LDHA, SLC16A1, PKM, HK1, and LDHB." (PMID 40539245, 2025). "In pancreatic cancer, for instance, the transcription factor Forkhead box Q1 (FOXQ1) directly activates LDHA transcription, thereby increasing lactate output and fueling tumor growth." (PMID 41152975, 2025). "NAC1 enhances the expression of lactate dehydrogenase A (LDHA) in tumor cells, leading to higher accumulation of lactic acid (LA), which results in altered cellular metabolism of cytotoxic T cells (CTLs) in the tumor microenvironment (TME)." (PMID 39773913, 2025). "Preclinical studies have demonstrated that LDHA inhibitors effectively reduce tumor growth, metastasis, and therapy resistance, making LDHA a central nexus in cancer metabolism and immune modulation." (PMID 40433363, 2025). "Tumor cells enhance lactate accumulation and sustain proliferative capacity by upregulating LDHA expression and enzymatic activity." (PMID 41152975, 2025). "Recent studies have demonstrated that Oxamate, a glycolytic inhibitor targeting LDHA, exerts anti-tumor effects in several cancers, including gastric and lung malignancies." (PMID 40565174, 2025). "In animal models, targeting lactate metabolism (such as inhibiting LDHA or B7-H3) significantly suppresses tumor growth and activates tumor-infiltrating CD8+ T cells, providing a new strategy for combined immunotherapy." (PMID 41181157, 2025). "LDHA inhibition attenuates tumor cell proliferation and promotes proliferation and infiltration of anti-tumor T lymphocytes by reducing lactate production." (PMID 40630951, 2025). "Research has found that LDHA inhibitors exhibit significant anti-tumor effects in certain tumor types and are undergoing preclinical validation." (PMID 41458606, 2025). "MYC subsequently promotes expression of glycolytic genes like LDHA, markedly increasing lactate production and glucose uptake, thereby accelerating tumor cell proliferation and invasion." (PMID 41020873, 2025). "In CRC, inhibitors targeting LDHA, such as oxamate, significantly inhibit glycolysis and reduce ATP production when combined with metformin, thereby suppressing tumor growth." (PMID 41020873, 2025). "Intriguingly, following the knockout of LDHA in macrophages, it was seen that the PD-L1 expression in tumor cells underwent a marked reduction, with a augmentation in T cells' anti-tumor activity." (PMID 39897050, 2025).
tumor (continued). "LDHA overexpression plays a critical role in promoting cancer progression, and its inhibition suppresses tumor growth." (PMID 41163796, 2025). "LDHA is often overexpressed in many cancers and acts as a biomarker for tumor progression and prognosis." (PMID 40619414, 2025). "These hypoxic tumor cells primarily depend on anaerobic glycolysis, converting pyruvate to lactate via lactate dehydrogenase A (LDHA), followed by export through monocarboxylate transporter 4 (MCT4)." (PMID 40948941, 2025). "In particular, anoxic tumor cells use lactate dehydrogenase A (LDHA) for lactate anabolism, which enters intercellular matrix through MCT4 and is taken up through MCT1 by aerobic tumor cells." (PMID 39934144, 2025). "The inhibition of LDHA enhances the efficacy of anti-PD-1 treatment by boosting the anti-tumor immune response." (PMID 40535811, 2025). "LDHA promotes lactate production to support the energy demands under hypoxia, while acidifying the microenvironment to promote tumor invasion." (PMID 40464853, 2025). "Tumor cells predominantly rely on aerobic glycolysis, known as the “Warburg effect,” converting glucose to lactate via LDHA, even in normoxic conditions." (PMID 40433363, 2025). "A similar mechanism is more pronounced in the TME: tumor-associated macrophages (TAMs) are stimulated by proinflammatory factors such as IL-6 and TNF-α to upregulate LDHA expression through HIF-1α, resulting in lactate accumulation." (PMID 40843350, 2025). "We also found the sphere formation abilities, CSC phenotypes and tumor initiating capacity were positively regulated by LDHA, suggesting that LDHA plays a critical role in the response to gemcitabine and the CSC properties of PDAC cells." (PMID 39930542, 2025). "For example, in pancreatic cancer, inhibiting the expression of NR3C2 leads to the upregulation of glycolytic enzymes HK1, HK2, and LDHA, promotes glucose uptake and lactate production and accelerates tumor growth." (PMID 41219936, 2025). "It summarized the recent literature on the LDHA expression, its regulation by transcription factors and non-coding RNAs, and its role in tumor stemness and microenvironment." (PMID 41422325, 2025). "LDHA (lactate dehydrogenase A) accelerates lactate production by promoting aerobic glycolysis (Warburg effect) during tumor development and maintains the energy supply in anoxic environment." (PMID 41271615, 2025). "Tumor-derived G-CSF and GM-CSF are typically high in glycolysis along with the abundant LDHA, which further promotes the recruitment of MDSCs and immunosuppression." (PMID 40230883, 2025). "The silencing of LDHA attenuates lactate production and subsequently inhibits the proliferative rate of tumor cells." (PMID 40165895, 2025). "Treatment with RSL3 effectively suppressed tumour growth in control tumours; however, its efficacy was significantly attenuated in LDHA‐overexpressing tumours." (PMID 41399129, 2025). "FX-11 is a selective LDHA inhibitor that exerts anti-tumor effects by inhibiting glycolysis and reducing lactate production." (PMID 40584617, 2025). "According to specific research, AP-1 and HIF-1α frequently cooperate to activate LDHA transcription and increase tumor cells’ ability to produce lactate." (PMID 40917751, 2025). "By catalyzing the conversion of pyruvate to lactate, LDHA accelerates glycolysis, providing both energy and biosynthetic intermediates necessary for sustaining rapid tumor growth and resisting radiotherapy." (PMID 41441035, 2025). "Restoring T cell anti-tumor function and reversing tumor acidity can be achieved by siRNA-mediated LDHA silencing." (PMID 40230883, 2025). "Genetic silencing of LDHA has been shown to suppress glycolysis and reduce lactate production across various tumor types, thereby attenuating tumor growth." (PMID 41152975, 2025).
tumor (continued). "Cyclin G2 inhibits the Warburg effect by blocking LDHA Y10 phosphorylation, thereby reversing the immunosuppressive microenvironment and halting tumor progression with a stronger anti-tumor effect when combined with anti-PD-177." (PMID 39897050, 2025). "Experiments such as using CRISPR-Cas9 system to knockout FGFR1 gene in DU145 to generate a new experiment system—FGFR1 null DU145 cells are needed to confirm the link between FGFR1 and LDHA with tumor cell phenotype." (PMID 40995571, 2025). "Specific inhibition or knockdown of LDHA is able to delay tumor growth and rescue sensitivity of chemotherapy resistance in multiple myeloma." (PMID 40612109, 2025). "Expectedly, LDHA KD downregulated the intratumoral lactate levels in both human and mouse transplanted tumor samples." (PMID 40139191, 2025). "For example, Oxamate acts as a pyruvate-competitive inhibitor of LDHA and has been shown to inhibit tumor cell proliferation." (PMID 40034817, 2025). "Galloflavin inhibits LDHA activity through direct binding, reducing lactate production and inducing apoptosis in tumor cells." (PMID 40034817, 2025). "The phosphoinositide 3-kinase (PI3K)/protein kinase B (Akt) pathway further supports this process by promoting LDHA-mediated conversion of pyruvate to lactate, contributing to tumor-specific accumulation of glycolytic end-products." (PMID 40842995, 2025). "Inhibiting LDHA has been shown to enhance T-cell-mediated immunity by reducing lactate buildup in the tumor microenvironment." (PMID 40260244, 2025). "Among the LDH isoforms, LDHA plays a pivotal role in tumor metabolism by catalyzing the conversion of pyruvate to lactate, thereby sustaining glycolysis through NAD+ regeneration while simultaneously acidifying the tumor microenvironment (TME)." (PMID 40565047, 2025). "Lactate dehydrogenase A (LDHA) and lactate transporters, including SLC16A3, have, to mention a few, been linked to tumor aggressiveness and poor clinical outcomes." (PMID 41422325, 2025). "These tumours were subsequently examined for their expression of FOXO3a, LDHA and miR-4259 by Western blotting and RT-qPCR, respectively." (PMID 39930542, 2025). "When TIA1 was silenced, BCG lost its efficacy: Sh-mTia1 tumors retained intense photon flux, persistent tumor architecture, high LDHA/HK2/PKM2 levels, and unaltered lactate output." (PMID 41300366, 2025). "In drug development, natural compounds (e.g., curcumin, quercetin) and several small-molecule inhibitors have been shown to directly suppress LDHA activity, shifting tumor metabolism from glycolysis toward mitochondrial OXPHOS." (PMID 41415548, 2025). "Developing tumor-specific delivery systems (such as nanoparticles targeting tumor cells) or prodrug design (such as LDHA inhibitors activated in a low-pH microenvironment) is an important research direction." (PMID 40426972, 2025). "For in vivo assays, we first demonstrated that LDHA level was markedly reduced in circSMPD4 knockout tumor." (PMID 40940312, 2025). "In the myCAF-rich subtype, we identified classic poor prognosis genes, such as LDHA, further reinforcing the notion that this subtype represents a more common tumor microenvironment." (PMID 40303408, 2025). "Ultimately, circSMPD4 promotes HCC immune evasion and progression through an LDHA‐mediated tumor metabolism and immunosuppression axis." (PMID 40940312, 2025). "Single-cell sequencing of tumor infiltrates immune cells in PDAC patients showed that neutrophil-like differentiated HL-60 cells(dHL-60) overexpressed the glycolytic enzyme LDHA, along with an upregulation of the glycolysis signature." (PMID 39897050, 2025). "Recent reviews highlight that inhibitors of LDHA or MCT1/MCT4 not only reduce tumor-cell growth but also “trap” the immunosuppressive tumour microenvironment and enhance immunotherapy efficacy." (PMID 41394868, 2025).